SULT1A1 (sulfotransferase family 1A member 1)
Diseases named in the same sentence as SULT1A1 in open-access papers (continued):
Sharing a sentence is not in itself a finding about the gene and the disease.
glioblastoma (1 paper, 2011). The most malignant astrocytic tumor (WHO grade IV). "Meanwhile, the expression patterns of three SULTs (SULT1A1, 1C2 and 4A1) in human glioblastoma tumors were profiled immunohistochemically." (PMID 22096581, 2011). "Immunohistochemical staining showed that 42.0%, 27.1% and 19.6% of 149 glioblastoma cases produced similar SULT1A1, 1C2 and 4A1 levels as that of tumor-surrounding tissues." (PMID 22096581, 2011).
HIV-1 infection (1 paper, 2016). The type species of lentivirus and the etiologic agent of acquired immunodeficiency syndrome (AIDS). "To further validate the role of SULT1A1 during HIV-1 infection, we next investigated the impact of knocking down expression of this protein on infection of MDMs by replication-competent HIV-1." (PMID 26906565, 2016).
insomnia (1 paper, 2016). A sleep disorder characterized by difficulty in falling asleep and/or remaining asleep. "Lower number of A alleles at rs750155, which would be expected to result in decreased SULT1A1 activity in whites, was associated with worsening insomnia from baseline to 48 months (P = 0.034)." (PMID 27300114, 2016). "Using a candidate gene approach, we identified an association between the number of SULT1A1 G alleles at rs9282861 and age at menopause, as well as insomnia and night sweats before initiation of HT." (PMID 27300114, 2016). "Of these two women in the placebo group, one experiencing both severe hot flashes and insomnia had two copies of SULT1A1, and was heterozygous at rs3760091, homozygous A at rs750155, and homozygous G at rs9282861." (PMID 27300114, 2016). "The second woman was also experiencing insomnia and had three copies of SULT1A1, was homozygous (for all three copies) G at rs3760091, had 2 G and 1 A at rs750155, and had 2 G and 1 A at rs9282861." (PMID 27300114, 2016).
intrahepatic cholangiocarcinoma (1 paper, 2025). A carcinoma that arises from the intrahepatic bile duct epithelium in any site of the intrahepatic biliary tree. "For intrahepatic cholangiocarcinoma (PDC000356), key proteins such as SULT1A1 were identified as tumor suppressors linked to chemoresistance and sulfonation-driven metabolic regulation." (PMID 40597613, 2025).
liver cancer (1 paper, 2025). An epithelial or non-epithelial malignant neoplasm that arises from the liver. "Enzyme-activated anticancer drugs, where a specific enzyme SULT1A1 converts a class of compounds into anticancer agents, have demonstrated the ability to kill liver cancer cells in cell and mouse models, potentially representing a new direction for future liver cancer treatment." (PMID 40308492, 2025).
oral cancer (1 paper, 2012). "The aim of this study was to investigate the association between Arg213His SULT1A1 gene polymorphism and oral cancer, and to explore any interaction between this polymorphism and smoking with regard to oral cancer risk." (PMID 23264952, 2012). "Among individuals who had at least one SULT1A1*2 allele (genotypes Arg/His and His/His), the risk of oral cancer associated with smoking revealed an OR = 4.50 (95% CI = 2.09–9.69) for smokers, and OR = 1.17 (95% CI = 0.46–2.95) for former smokers." (PMID 23264952, 2012). "Association between smoking and oral cancer according to Arg213His SULT1A1 polymorphism, oral cancer cases and controls, Rio de Janeiro, Brazil, 1999–2002." (PMID 23264952, 2012). "Since SULT1A1 is involved in bioactivation of tobacco smoke pro-carcinogens and smoking is a major oral cancer risk factor, Arg213His SULT1A1 polymorphism can hypothetically be associated with oral carcinogenesis in smokers." (PMID 23264952, 2012). "The magnitude of association between cigarette smoking and oral cancer was higher in individuals with a SULT1A1*1 isoform (wild type, genotype Arg/Arg) (OR = 10.19, 95% CI = 3.90–26.61) than in those with at least one SULT1A1*2 allele (genotypes Arg/His + His/His) (OR = 4.50, 95% CI =2.09–9.69)." (PMID 23264952, 2012). "However, the risk of developing oral cancer in betel quid chewers and smokers seemed to be lower in SULT1A1*2 isoform patients comparatively to those with a wild type (OR = 0.58, 95% CI = 0.15–2.28)." (PMID 23264952, 2012). "Results of this study suggest that Arg213His SULT1A1 polymorphism may modulate susceptibility to oral cancer in smokers." (PMID 23264952, 2012). "Distribution of oral cancer cases and controls according to sex, age, skin color, smoking, alcohol intake, and Arg213His SULT1A1 genotype, Rio de Janeiro, Brazil, 1999–2002." (PMID 23264952, 2012). "With regard to oral cancer, SULT1A1*2 isoform has only been studied in Taiwan." (PMID 23264952, 2012).
renal fibrosis (1 paper, 2023). A final common manifestation of a wide variety of chronic kidney diseases characterized by glomerulosclerosis and tubulointerstitial fibrosis. "In this study, we investigated the toxicopathological role of IS in renal fibrosis using Sult1a1-KO mice and the underlying mechanisms." (PMID 37511089, 2023). "We further confirmed the effect of Sult1a1 deficiency on UUO-induced renal fibrosis using Sirius red staining and the protein expression of α-SMA." (PMID 37511089, 2023). "We investigated the pathological role of IS on renal fibrosis and its underlying mechanisms using Sult1a1-KO mice." (PMID 37511089, 2023). "We investigated the toxicopathological role of IS in renal fibrosis using Sult1a1-KO mice and the underlying mechanisms." (PMID 37511089, 2023). "To investigate the effect of Sult1a1 deficiency in the UUO model, we examined the gene expression of renal fibrosis and inflammatory cytokines using RT-PCR." (PMID 37511089, 2023). "The inactivation of Wnt/β-catenin signaling is involved in decreasing renal fibrosis; treating Sult1a1-KO mice with rhEPO further attenuated UUO-induced renal fibrosis, indicating the possibility of combination therapy in patients with CKD." (PMID 37511089, 2023). "Our findings confirmed the pathological role of IS in renal fibrosis and identified SULT1A1 as a new therapeutic target enzyme for preventing and attenuating renal fibrosis." (PMID 37511089, 2023). "Our findings confirmed the direct pathological role of IS in kidney inflammation and fibrosis, identifying SULT1A1 as a new therapeutic target for preventing or attenuating renal fibrosis." (PMID 37511089, 2023). "Sult1a1-KO mice exhibited reduced renal fibrosis, inflammation, and apoptosis and improved EPO production." (PMID 37511089, 2023). "We considered whether the Wnt/β-catenin signal affects the attenuated renal fibrosis in Sult1a1-KO mice." (PMID 37511089, 2023). "Its effect on renal fibrosis would be investigated using Sult1a1-KO mice in the future." (PMID 37511089, 2023). "Thus, UUO-induced renal fibrosis was alleviated in Sult1a1-KO mice with a decreased accumulation of IS." (PMID 37511089, 2023). "Sirius red staining revealed similar results as those observed for α-SMA expression, indicating that combining Sult1a1-KO and rhEPO treatment might prevent renal fibrosis more effectively." (PMID 37511089, 2023). "Furthermore, in Sult1a1-KO mice, rhEPO administration suppressed renal fibrosis more effectively." (PMID 37511089, 2023). "Renal fibrosis markers, col1a1 and fibronectin, were highly expressed in the WT UUO group but were significantly suppressed in the Sult1a1-KO UUO group." (PMID 37511089, 2023). "In Sult1a1-KO mice, EPO mRNA expression was improved considerably; UUO-induced renal fibrosis was further attenuated by recombinant human erythropoietin (rhEPO)." (PMID 37511089, 2023). "Thus, we examined whether UUO-induced renal fibrosis could be improved in Sult1a1-KO mice." (PMID 37511089, 2023). "Consistently, our results indicate that Sult1a1-KO partly improved EPO production and progressive renal fibrosis was further suppressed by the administration of rhEPO to Sult1a1-KO mice." (PMID 37511089, 2023). "In conclusion, Sult1a1-KO mice demonstrated less IS build-up, which reduced UUO-induced renal fibrosis; infiltrating CD206+ macrophages may aid inflammation and suppress renal fibrosis in Sult1a1-KO mice." (PMID 37511089, 2023).
Renal insufficiency (1 paper, 2020). A reduction in the level of performance of the kidneys in areas of function comprising the concentration of urine, removal of wastes, the maintenance of electrolyte balance, homeostasis of blood pressure, and calcium metabolism. "Taken together, our results suggest that low expression of XDH, CYP2E1, and SULT1A1, combined with the absence of renal AhR, may explain the low level of renal insufficiency observed in AhR−/− mice in the adenine-induced CKD model." (PMID 32260098, 2020).
Sepsis (1 paper, 2019). Sepsis is defined as life-threatening organ dysfunction caused by a dysregulated host response to infection. "Interestingly, several of the genes linked to glucocorticoid signaling (Arl4d, Cdkn1a, Ddit4, Fkbp5, Gjb6, Il6ra, Klf15, Nfkbia, Rhob, Sdc4, Sgk1, Sult1a1, Tob2, Wipf3) and apoptotic process were still upregulated 4 days post-sepsis." (PMID 31278440, 2019).
Tension-type headache (1 paper, 2022). A type of headache that last hours with continuous pain of mild or moderate intensity, bilateral location, a pressing/tightening (non-pulsating) quality and that is not aggravated by routine physical activity such as walking or climbing stairs. "Reduced SULT1A1 enzyme activity was shown in migraineurs compared to tension-type headache patients and healthy control subjects." (PMID 35282834, 2022).
cancer (35 papers, 2005 to 2025). A tumor composed of atypical neoplastic, often pleomorphic cells that invade other tissues. "SULT1A1 is responsible for the sulfonation of xenobiotics and has been implicated in several cancers by activating carcinogens." (PMID 38742104, 2024). "Together with previous findings on SULT1A1 R213H, this study hereby contributes to a better understanding regarding the role of SULT1A1 mutation in cancer development." (PMID 31835852, 2019). "This SULT1A1 Arg213His (rs9282861) polymorphism is reported to be associated with increased risk of various cancer types." (PMID 28357488, 2017). "Our study demonstrated that NSC-743380's anticancer activity is causally associated with SULT1A1 expression in cancer cells and that SULT1A1 expression can be used as a biomarker to predict response or identify responders to NSC-743380." (PMID 25514600, 2015). "Several studies have investigated the association of SULT1A1 variants with cancer, and the results have been controversial." (PMID 25992585, 2015). "The SULT1A1 Arg213His (rs9282861) polymorphism is reported to be associated with many kinds of cancer risk." (PMID 25225888, 2014). "The Arg213His polymorphism, the most widely studied polymorphism within SULT1A1 gene, can reduce enzyme activity and thermostability, and consequently results in an individual's susceptibility to cancer." (PMID 25225888, 2014). "A total of 91 studies focusing the association between the SULT1A1 Arg213His polymorphism and cancer risks were identified." (PMID 25225888, 2014). "SULT1A1 is an important member of the sulfotransferase family involving in the pathogenic process of various cancers." (PMID 25225888, 2014). "Overall and subgroup meta-analysis of the association between SULT1A1 Arg213His polymorphism and cancer risk under genetic models." (PMID 25225888, 2014). "This present meta-analysis, including 16733 cases and 23334 controls from 53 case-control studies, explored the association between the SULT1A1 Arg213His polymorphism and cancer risk." (PMID 25225888, 2014). "Some studies have shown that this genetic polymorphism leads to a decrease in enzymatic activity of SULT1A1 and the sulfonation efficiency thus associating with susceptibility to several cancers." (PMID 25225888, 2014). "Overall, we found SULT1A1 Arg213His polymorphism can increase cancer risk under heterozygous (OR = 1.09, 95% CI = 1.01–1.18, P = 0.040), dominant (OR = 1.10, 95% CI = 1.01–1.19, P = 0.021) and allelic (OR = 1.08, 95% CI = 1.02–1.16, P = 0.015) models." (PMID 25225888, 2014). "To elucidate the effect of Arg213His polymorphism of SULT1A1 in tobacco users, we have studied a group of patients with multiple primary cancers, where at least one of the primary cancers was a TRC." (PMID 18854828, 2008). "In this case–control study, we have examined the association of SULT1A1 Arg213His (SULT1A1*2) polymorphism in 132 patients with tobacco-related multiple primary cancers and 198 cancer-free controls." (PMID 18854828, 2008). "The risk association of SULT1A1*2 with cancers of the UADT and lung is expected from its known role in tobacco detoxification." (PMID 18854828, 2008). "The majority of the genes synergistically upregulated by inhibition of both PD-L1 and TGF-β were associated with metabolic pathways (Nqo1, Hmgsc1, Sult1a1, Pla2g7, Ugt1A5, Ugt2B5, Abcb1a), that enhance cancer cell proliferation, invasion, and metastasis (Fig-6D)." (PMID 38516270, 2024). "In this study, we considered SULT1A1 R213H, which is associated with various cancers." (PMID 31835852, 2019). "In conclusion, our meta-analysis suggests that the SULT1A1 Arg213His polymorphism may contribute UADT cancer risk." (PMID 25225888, 2014). "The overall and subgroup heterogeneity test of the SULT1A1 Arg213His polymorphism on cancer risk." (PMID 25225888, 2014). "Our results suggested that the SULT1A1 Arg213His was associated with UADT cancer risk." (PMID 25225888, 2014).
cancer (continued). "The mutation in the SULT1A1 gene would affect an individual’s capacity to efficiently sulfate endogenous compounds, drugs and xenobiotics, and consequently result in an individual’s susceptibility to cancer." (PMID 24842778, 2014). "The association between Arg213His SULT1A1 polymorphism and other cancer types has been mixed." (PMID 23264952, 2012). "In this case–control study, we have examined the association of SULT1A1 Arg213His polymorphism with tobacco carcinogenesis using a unique group of individuals with multiple tobacco-related primary cancers and have used a meta-analysis approach to confirm our findings." (PMID 18854828, 2008). "We therefore set out to determine whether specific tumor characteristics and the age of cancer onset were influenced by the SULT1A1 or UGT1A1 alleles." (PMID 16280036, 2005). "Likewise, a large number of congeners (>140) of YC-1 (containing furfuryl alcohol in their structure) and AHBAs (sharing a core structure of 4-Amino-2-HaloBenzyl Alcohol) were much more cytotoxic in two cancer cell lines with high SULT1A1 expression than in two similar SULT1A1-deficient lines." (PMID 39611595, 2024). "Accordingly, the uncharged phenolic compounds are preferred by SULT1A1, where the mutation R213H disorders the plasticity of substrates binding loops and increased the hydrophilicity of the pocket, affecting the sulfonation process, and thus contributes in cancer progression." (PMID 31835852, 2019). "We found that RITA, AF, and ONC-1 inhibit TrxR1 and induce oxidative stress in cancer cells in a SULT1A1-dependent manner." (PMID 32727562, 2020). "To validate this correlation of anticancer activities by the compounds with SULT1A1 expression, we tested the effects of RITA, AF, and ONC-1 in nine cancer cell lines with different SULT1A1 levels." (PMID 32727562, 2020). "Taken together, our data demonstrate that 4OH-TMX treatment results in the propagation of cancer cells with increased SULT1A1 expression." (PMID 32727562, 2020). "Knockdown of the SULT1A1 in the NSC-743380 sensitive cancer cell line rendered it resistance to NSC-743380." (PMID 25514600, 2015). "Ectopic expression of SULT1A1 in NSC743380 resistant cancer cells dramatically sensitized the resistant cells to NSC-743380." (PMID 25514600, 2015). "SULT1A1 was expressed in NSC-743380–sensitive cell lines but was undetectable in resistant cancer cells." (PMID 25514600, 2015). "TF profiling array data demonstrated that NFI in high-SULT1A1-expressing ZR-75-1 breast cells was expressed more than in low-SULT1A1-expressing non-cancer MCF-10A cells." (PMID 24393253, 2014). "The authors of this study conducted computational analyses on compounds that had been tested for cytotoxicity in many cancer cell lines; they identified hundreds of compounds whose activity in different cell lines showed high correlation with either SULT1A1 transcript levels or YC-1 sensitivity." (PMID 39611595, 2024). "As for example, possible interaction of anti-cancer anti-estrogenic drug tamoxifen with the SULT1A1 may be considered here." (PMID 39132498, 2024). "Among the previously found cancer-hallmark survival-related genes (PAK6, SLC11A1, SULT1A1 and TUBB6), we observed that their differential expression still had a significant impact on survival for three of the genes (PAK6, SLC11A1 and TUBB6), when considering stage stratification." (PMID 34885088, 2021). "As the sulfation of 4-hydroxytamoxifen by SULT1A1 decreases therapeutic efficacy of tamoxifen in cancer cells, 6-PN and 8-PN, which increase the SULT activity in the proliferating cells, might reduce the tamoxifen treatment efficacy." (PMID 32708388, 2020). "Thus, expression of SULT1A1 in cancer cells is required for NSC-743380's anticancer activity and can be used as a biomarker for identification of NSC-743380 responders." (PMID 25514600, 2015).
cancer (continued). "The present meta-analysis suggests that SULT1A1 Arg213His polymorphism plays an important role in carcinogenesis, which may be a genetic factor affecting individual susceptibility to UADT cancer." (PMID 25225888, 2014). "Together, the results from this study and the studies on tamoxifen and aminoflavone suggest that intratumoral expression of SULT1A1 may serve as a bioactivator for some anticancer agents and as a biomarker to identify responders to those therapeutics in a subgroup of cancer patients." (PMID 25514600, 2015). "We found that SULT1A1 and SULTE1 were expressed at similar levels in cancer as compared to normal kidney tissue." (PMID 31655797, 2019). "Considering our findings that SULT1A1 expression is induced by 4OH-TMX treatment, and that SULT1A1 expression is required for RITA, AF, ONC-1 antitumor activity, we hypothesized that the compounds would kill TMX-pretreated cancer cells more efficiently." (PMID 32727562, 2020). "Among these, sulfotransferases (SULT1A1, SULT1A2, SULT1A3) and aldo-keto reductases (AKR1C1, AKR1C2, AKR1C3) were shown to contribute to disease progression and/or represent therapeutic targets in hormone-dependent forms of cancer, including EOC." (PMID 26372729, 2015). "Furthermore, a subsequent analysis on the possible role of the altered genes in CRC and IPD data sets in the survival of cancer patients (TCGA-COAD data sets) pointed to a significant influence on survival for eight of these genes (TUBB6, PAK6, SULT1A1, SLC11A1, TRAP1, FAM50B, SPON2, FES)." (PMID 34885088, 2021).